ELK1 (ETS transcription factor ELK1)
Diseases named in the same sentence as ELK1 in open-access papers (continued):
Sharing a sentence is not in itself a finding about the gene and the disease.
bladder cancer (22 papers, 2015 to 2025). "We also previously demonstrated activation of ELK1 by androgen-mediated AR signals in bladder cancer cells, as well as a significant association between the expression levels of p-ELK1 and AR in bladder tumor tissue specimens." (PMID 29518027, 2018). "Rs2978974 in the promoter region of PSCA showed low linkage disequilibrium with rs2294008 and the Ars2978974 allele was shown to contribute to bladder cancer susceptibility, presumably due to the loss of binding of ELK1 or other ETS proteins to the PSCA promoter." (PMID 27050280, 2016). "Silodosin treatment resulted in significant reduction in the viability and migration of AR-positive bladder cancer cells in a dose-dependent manner, while inhibiting ELK1 expression." (PMID 40486871, 2025). "As a transcription factor, ELK1 can trigger downstream target oncogenes, including c-Fos, and promote the growth of bladder cancer cells with functional androgen receptors." (PMID 34970415, 2021). "Inactivation of ELK1 has been found to enhance the cytotoxic activity of a common chemo drug, cisplatin, to bladder cancer cells." (PMID 34540820, 2021). "Silodosin increased the sensitivity of bladder cancer cells to cisplatin by decreasing the expression of ELK1, C-FOS, and NF-κB." (PMID 34988010, 2021). "Previous studies have demonstrated the oncogenic role exerted by AP2α and ELK1 in colorectal and bladder cancer." (PMID 35317119, 2021). "ELK1 has also been elucidated to play a crucial role in the tumorigenesis and progression of bladder cancer." (PMID 32670874, 2020). "ELK1 triggers a proto-oncogene c-Fos, downstream target, by which ELK1 stimulates the growth of bladder cancer cells." (PMID 31772143, 2019). "Using preclinical models, we have recently found that ELK1, a transcriptional factor that activates downstream targets, including c-fos proto-oncogene, induces bladder cancer outgrowth." (PMID 29518027, 2018). "Using in vitro and in vivo models for bladder cancer, we have recently found that ELK1 activation correlates with the induction of cell proliferation, migration, and invasion, as well as resistance to cisplatin cytotoxicity." (PMID 29518027, 2018). "The current results also support our in vitro and in vivo findings in bladder cancer and further suggest that p-ELK1 overexpression serves as a predictor of poor prognosis in patients with UUTUC." (PMID 29518027, 2018). "The current results thus support our previous observations in bladder cancer and further suggest that phospho-ELK1 overexpression serves as a predictor of poor prognosis in patients with UUTUC." (PMID 29518027, 2018). "Previous studies using ELK1 depletion methods have demonstrated that both prostate and bladder cancer cells require ELK1 for androgen-dependent growth (31, –, 33)." (PMID 27793987, 2016). "Other investigators have extended these studies to demonstrate that ELK1 is similarly required for androgen-dependent growth of bladder cancer." (PMID 27793987, 2016). "In this study, we aim to investigate the functions of ELK1 in bladder cancer growth and their regulation by AR signals." (PMID 26342199, 2015). "Subsequent immunohistochemistry in bladder cancer specimens from patients who received neoadjuvant chemotherapy revealed that phospho-ELK1 positivity strongly correlated with chemoresistance." (PMID 26770009, 2015). "Little is known about biological significance of ELK1, a transcriptional factor that activates downstream targets including c-fos proto-oncogene, in bladder cancer." (PMID 26342199, 2015). "On the other hand, the expression levels of ELK1 and p-ELK1 have been determined in bladder cancer cell lines." (PMID 26342199, 2015). "We assessed the effects of androgen on ELK1 expression by reverse transcription (RT)-polymerase chain reaction (PCR), western blotting, and immunofluorescence in bladder cancer cells treated with DHT and/or an AR antagonist hydroxyflutamide (HF)." (PMID 26342199, 2015).
bladder cancer (continued). "DHT increased ELK1 gene expression in two AR-positive bladder cancer sublines, UMUC3-control-shRNA (3.4-fold) and 647V-AR (3.2-fold), but not in AR-negative sublines." (PMID 26342199, 2015). "Accordingly, not only AR or ELK1 signaling but also their interaction offers a therapeutic target for bladder cancer." (PMID 26342199, 2015). "It is thus possible that ELK1 and AR serve each other as transcriptional coactivators in bladder cancer cells." (PMID 26342199, 2015). "Our data in bladder cancer cells indicate that androgen induces the expression and activity of ELK1." (PMID 26342199, 2015). "To see if ELK1 is involved in bladder cancer cell migration and invasion, we performed a scratch wound healing assay and a transwell invasion assay, respectively, in UMUC3 and 647V-AR expressing either ELK1-shRNA or control-shRNA." (PMID 26342199, 2015). "In the current study, ELK1 silencing in AR-positive bladder cancer lines cultured with androgen resulted in significant decreases in cell migration and invasion as well as the expression and enzymatic activity of MMP-2/MMP-9." (PMID 26342199, 2015). "We therefore decided to further study ELK1 as a potential target of androgen/AR signals in bladder cancer." (PMID 26342199, 2015). "In AR-positive bladder cancer cell lines, dihydrotestosterone treatment increased ELK1 expression (mRNA, protein) and its nuclear translocation, ELK1 transcriptional activity, and c-fos expression, which was restored by an anti-androgen hydroxyflutamide." (PMID 26342199, 2015). "These in vivo data further suggest that ELK1 silencing inhibits the development and progression of bladder cancer." (PMID 26342199, 2015). "Accordingly, ELK1 inhibition, together with AR inactivation, has the potential of being a therapeutic approach for bladder cancer." (PMID 26342199, 2015). "We additionally found that ELK1 silencing induced apoptosis of bladder cancer cells that possessed a functional AR and were cultured with FBS containing androgens but did not modulate the cell-cycle status." (PMID 26342199, 2015). "Androgens also failed to significantly induce AR transcriptional activity in ELK1 knockdown bladder cancer cells." (PMID 26770009, 2015). "We additionally found in bladder cancer cells that androgens induced nuclear translocation of ELK1 and its transactivation." (PMID 26342199, 2015). "A chromene derivative 2j, which could function as a selective inhibitor for AKR1C3, was found to inhibit the expression of AR and ELK1 in bladder cancer cells and enhance the cytotoxic activity of gemcitabine + cisplatin." (PMID 40486871, 2025). "A selective α1-blocker silodosin, which could down-regulate ELK1 expression, thus increased cisplatin sensitivity in ELK1-positive bladder cancer cells." (PMID 40486871, 2025). "miR-2682-5p could also form a feedback cycle with ETS transcription factor ELK1 (ELK1)/lncRNA-SNHG7 to enhance bladder cancer cell growth." (PMID 35733138, 2022). "Interestingly, the expression of ELK1, a marker for tumor progression post radical cystectomy for bladder cancer, is inhibited by Silodosin, which also inhibits ELK1 bladder cancer cell survival and migration." (PMID 34284799, 2021). "A recent study reported that ELK1 is closely related to chemoresistance of cancer cells and depletion of ELK1 could promote the chemosensitivity to CDDP in bladder cancer cells via increment of bladder cancer cell proliferation." (PMID 33621196, 2021). "Thus, ELK1 has been suggested to not only promote urothelial cancer progression, but also function as an important prognosticator for bladder cancer." (PMID 29518027, 2018). "In addition, we have recently demonstrated, in bladder cancer cells, that androgens up-regulate ELK1, a transcription factor whose downstream target is c-fos proto-oncogene, and that ELK1 inactivation results in enhancement of the cytotoxic activity of CDDP." (PMID 27322140, 2016).
bladder cancer (continued). "Indeed, ELK1 inactivation resulted in enhancement of the cytotoxic activity of cisplatin in bladder cancer cells." (PMID 26770009, 2015). "Thus, ELK1 and AR signals appear to require each other for their functions at least in bladder cancer cell proliferation." (PMID 26342199, 2015). "In the current study, we investigated whether androgen could activate ELK1, as a downstream target of AR, in bladder cancer cells as well as whether ELK1 could affect their proliferation and migration in the presence and absence of androgen." (PMID 26342199, 2015). "ELK1 is indeed activated in bladder cancer, which is further induced by AR activation." (PMID 26342199, 2015). "We thus narrowed down the candidate to ELK1 and further investigated whether ELK1 could be activated by androgen-mediated AR signaling in bladder cancer cells and thereby affected tumor progression." (PMID 26342199, 2015). "Similarly, androgen appears to require ELK1 to induce bladder cancer cell proliferation, while it can still increase the migration ability of ELK1-knockdown cells." (PMID 26342199, 2015). "Thus, AR activation is likely required for the regulation of bladder cancer cell growth by ELK1." (PMID 26342199, 2015). "We therefore investigated whether ELK1 could affect the viability and migration of AR-positive bladder cancer cells in the absence of androgens and whether androgen could enhance the viability and migration of AR-positive ELK1-shRNA-expressing bladder cancer cells." (PMID 26342199, 2015). "SNHG7 acts as a sponge for miR-2682-5p to enhance the expression of ELK1, and the high expression of SNHG7 promotes the growth, migration, and invasion of bladder cancer cells." (PMID 39195675, 2024). "For instance, we have demonstrated activation of ERBB2 and ELK1, both of which have also been shown to induce CDDP resistance, by androgens in AR-positive bladder cancer cells." (PMID 27322140, 2016). "At the same time, SNHG3/miR-2682-5p/HOXB8 axis, ELK1/lncRNA-SNHG7/miR-2682-5p feedback loop, and LINC01006/miR- 2682-5p/HOXB8 axis can promote the proliferation and migration of oral squamous cell carcinoma, bladder cancer, and pancreatic cancer, respectively." (PMID 35465266, 2022). "We recently demonstrated that androgens activated ELK1 in bladder cancer cells and promoted the proliferation of only ELK1-positive cells and the migration/invasion of both ELK1-positive and ELK1-negative cells." (PMID 26770009, 2015). "Of note, activated AR is necessary for ELK1 to promote bladder cancer cell proliferation, but not cell migration." (PMID 26342199, 2015). "We also demonstrated that androgens failed to significantly increase the viability of bladder cancer cells expressing ELK1-shRNA, suggesting ELK1-dependent effects of androgens on cell proliferation." (PMID 26342199, 2015). "Importantly, ELK1 appears to require activated AR to regulate bladder cancer cell proliferation, but not cell migration." (PMID 26342199, 2015). "To determine whether ELK1 down-regulation exerts an influence on the proliferation of bladder cancer cells, we compared cell viability [by methyl thiazolyl disphenyl tetrazolium bromide (MTT) assay] and colony formation (by clonogenic assay) between ELK1-positive lines versus their knockdown lines." (PMID 26342199, 2015). "Thus, in contrast to its function in cell proliferation, ELK1 may not require activated AR to regulate bladder cancer cell migration." (PMID 26342199, 2015).
colorectal cancer (22 papers, 2015 to 2025). A primary or metastatic malignant neoplasm that affects the colon or rectum. "The activation of the ERK/ELK1/Snail signaling pathway underlies the promotive function of tumor-derived CXCL5 in colorectal cancer metastasis." (PMID 31772143, 2019). "Through in-depth research on colorectal cancer-associated macrophages, it discovers that Elk-1 expression is positively related to inhibitory receptor signaling regulatory protein-α (Sirpα) expression, which may be intimately connected with the difficulties in curing colorectal cancer malignancies." (PMID 36439106, 2022). "Specifically, AP2α and ELK1 form a regulatory network that facilitates the SIRPα expression in tumor-associated macrophages, which was associated with poor survival in colorectal cancer, suggesting that AP2α and ELK1 could promote the transcription of both H2A.Z isoforms." (PMID 35317119, 2021). "Overexpression of the ETS-domain containing protein (ELK-1) promoted the adhesion, migration, and invasion of colorectal cancer." (PMID 38656555, 2024). "We analyzed the effect of monensin on 12 cancer-related pathways and found that monensin inhibited the reporter activities for ElK1, Ap1 pathway, and to a lesser extent the Myc/max reporter activity in human colorectal cancer cells." (PMID 36896461, 2023). "One study reported the involvement of the ELK1/CHOP/DR5 pathway via ERK1/2 activation in G2/M arrest of colorectal cancer cells." (PMID 36689027, 2023). "A large number of studies have shown that ELK1 can be used as a cancer protein for many human cancers, including pancreatic cancer, colorectal cancer, gastric cancer, lung cancer, and nasopharyngeal carcinoma." (PMID 35962333, 2022). "Another study found miR-206 suppressed the Met/ERK/Elk-1/HIF-1α/VEGF-A pathway in CCL19-mediated colorectal cancer cells." (PMID 34697590, 2021). "Pharmaceuticals targeting ELK1 in lung, breast, and colorectal cancer." (PMID 40862737, 2025). "ELK1 has been reported several times in the context of Colorectal carcinoma (CRC)." (PMID 40862737, 2025). "As a transcription factor, ELK1 has been widely studied in colorectal cancer." (PMID 37547727, 2023). "Furthermore, Sp1 and Elk-1 bind to the caspase-8 promoter and induce apoptosis in colorectal cancer cells in response to SPARC treatment." (PMID 25693514, 2015). "Additionally, Elk1 has been reported to promote survival through autophagy regulation in colorectal cancer cells, a mechanism that could also be present here." (PMID 40699751, 2025). "Additionally, overexpression of CXCL5 enhanced the migration and invasion of colorectal cancer cells by inducing the epithelial-mesenchymal transition (EMT) through activation of the ERK/Elk-1/Snail pathway and the AKT/GSK3β/β-catenin pathway in a CXCR2-dependent manner." (PMID 28356111, 2017). "TRPM2-AS interacts with the transcription factor ELK1 in gastric cancer, while LINC01224 interacts with YY1 in colorectal cancer, both of which influence cell cycle progression and stress responses." (PMID 40149330, 2025). "Monensin was shown to target multiple cancer-related signaling pathways such as Elk1, AP1, as well as Myc/max, and suppressed IGF1R expression via increasing IGF1 in colorectal cancer cells." (PMID 36896461, 2023). "In addition, in response to secreted protein, acidic and rich in cysteine (SPARC) expression, Sp1 and Elk-1 bind to the caspase-8 promoter and induce apoptosis in MIP101 colorectal cancer cells." (PMID 25693514, 2015).
colon carcinoma (15 papers, 2013 to 2025). "We also analyzed associations between AKAP95 and B-Raf, ERK1/2, and Elk-1 in colon cancer tissue." (PMID 36691407, 2023). "NGF derived from has been shown to activate the TrkA/ERK/ELK1/ZEB1 signaling pathway in colon cancer cells." (PMID 38816365, 2024). "CXCL5 can promote colon cancer metastasis by activating the ERK/Elk‐1/Snail and AKT/GSK3β/β‐catenin signaling pathways." (PMID 37666495, 2024). "AKAP95, ERK1/2, ELK-1, and B-Raf expression levels in 64 colon cancer and 32 para-carcinoma samples were assessed." (PMID 36691407, 2023). "Coincidently, miR-21-5p was positively associated with the expression of NGF, p-ERK, p-ELK1, and ZEB1 in human colon cancer tissues." (PMID 36522730, 2022). "Meanwhile, the Schwann cells-derived NGF activated TrkA/ERK/ELK1/ZEB1 signaling pathway in colon cancer cells, which further enhanced the expression of exosomal miR-21-5p." (PMID 36522730, 2022). "In our study, we found that NGF obviously increased the phosphorylation of ERK and ELK1 in colon cancer cells through TrkA." (PMID 36522730, 2022). "In summary, our data demonstrated that NGF increased ZEB1 expression in colon cancer cells through TrkA/ERK/ELK1." (PMID 36522730, 2022). "miR-330-5p can affect the expression of ELK1 and thus affect the proliferation, migration, and invasion of colon cancer cells." (PMID 32908877, 2020). "Our results are consistent with those of a previous study in which overexpression of ETS2-DN and Elk1-DN significantly decreased the P5 promoter activity in colon cancer cells." (PMID 23840432, 2013). "Furthermore, we also observed that the expression level of total Elk1 was enhanced by KRASG12C mutation, which was consistent with a previous report in colon cancer." (PMID 37226642, 2023). "Therefore, we detected the expression of ELK1 and cMYC in colon cancer cells upon treatment with NGF." (PMID 36522730, 2022). "Furthermore, ZEB1 expression was decreased upon the knockdown of ELK1 in colon cancer cells, both at mRNA and protein levels." (PMID 36522730, 2022). "Similarly, Zhao and Dai have found that hsa_circRNA_000166 could promote cell proliferation, migration, and invasion by regulating miR-330-5p/ELK1 in colon cancers previously." (PMID 33376485, 2020). "HTLV-1 Tax acts on genes indirectly by binding several TFs, such as TCF3, ELK1, and MYC in colon cancer, as well as POLB, BUB3, and CDK4, according to the HTLV-1 infection signaling pathway." (PMID 39228892, 2024). "LPS also increased COX2, CXCL1, ELK1, ICAM1, TNFSF10 and ZFAND5 but decreased BCL2L1, CYP19A1 and E2F1 mRNA levels in the colon cancer cells." (PMID 37705049, 2023). "qPCR showed that LPS increased CXCL1, ELK1, ICAM1 and ZFAND5 mRNA levels, but decreased BCL2L1 and E2F1 mRNA levels in the colon cancer cells." (PMID 37705049, 2023). "The chi-square test identified that miR-21-5p was positively correlated with NGF, p-ERK, p-ELK1, and ZEB1 in the colon cancer specimens." (PMID 36522730, 2022). "Mechanistically, PKN2 suppresses the expression of IL4 and IL10 from colon cancer cells by inhibiting Erk1/2 phosphorylation, which is required for phosphorylation and binding of CREB and Elk-1 to the promoters of IL4 and IL10." (PMID 29368606, 2018). "JUN is overregulated in three of the five datasets and is related to: 1) colon cancer signaling pathways along with MYC; 2) the focal adhesion pathway along with ELK1; 3) pathways in cancer along with ELK1 and MYC; 4) EBV infection along with MYC; and 5) angiogenesis." (PMID 39228892, 2024). "The ERK pathway has also important roles in tumor immune invasion; however, AKAP95, ERK1/2, and Elk-1 expressions were not related to colon cancer invasion and metastasis but were possibly related to our low sample numbers." (PMID 36691407, 2023). "Furthermore, inhibition of ERK phosphorylation or knockdown of ELK1 reversed the effect of NGF on the proliferation, migration, and invasion of colon cancer cells." (PMID 36522730, 2022).
colon carcinoma (continued). "Moreover, knockdown of ELK1 reversed the effect of NGF on the proliferation, migration, and invasion of colon cancer cells." (PMID 36522730, 2022). "A network-based analysis of colon cancer splicing changes reported noteworthy differences in the induction of various transcription factors such as MYC and ELK1, and supported our findings with respect to the activation of signaling pathways upon PRPF overexpression." (PMID 28915620, 2017).